FIGNL1 (fidgetin like 1)
Description:
ATPase that maintains genome stability by acting as a key regulator of DNA double-strand break (DSB) repair via homologous recombination (HR). Regulates HR by mediating disassembly of RAD51 filaments from DNA and chromatin, thereby preventing DNA damage-independent RAD51 loading and persistent DNA accumulation of RAD51 recombinases. Also regulates HR during meiosis by mediating dissociation of DMC1 filaments from DNA (By similarity). May regulate osteoblast proliferation and differentiation (By similarity).
Tractability: Small molecule: a structure with a bound ligand is known; it has a high-quality binding pocket. PROTAC: UniProt records ubiquitination sites on it; ubiquitination databases record sites on it.
Gene: Protein-coding gene on chromosome 7 (50,444,128 to 50,450,406, reverse strand). Ensembl gene ENSG00000132436.
Subcellular location: Chromosome; Nucleus; Cytoplasm; Cytoplasm, perinuclear region
Pathways (Reactome):
DNA Repair: Resolution of D-loop Structures through Holliday Junction Intermediates
Reproduction: Meiotic recombination
Gene Ontology:
Molecular function: ATP hydrolysis activity; protein binding; protein-containing complex destabilizing activity; hydrolase activity; magnesium ion binding; microtubule severing ATPase activity; ATP binding
Biological process: cellular response to ionizing radiation; DNA recombinase disassembly; interstrand cross-link repair; negative regulation of double-strand break repair via homologous recombination; protein hexamerization; ATP metabolic process; double-strand break repair involved in meiotic recombination; homologous recombination; male meiotic nuclear division; microtubule severing; negative regulation of apoptotic process; osteoblast differentiation; osteoblast proliferation; regulation of cell cycle
Cellular component: chromatin; DNA repair complex; extracellular exosome; nuclear chromosome; nucleus; cytoplasm; nucleoplasm; perinuclear region of cytoplasm; chromosome
Genetic constraint (gnomAD): Loss-of-function variants: 12 observed, 31.62 expected, observed/expected ratio (o/e) 0.38, 90% interval 0.24 to 0.62. The upper end of that interval is the gene's LOEUF score, 0.62, which puts it in group 2 of 6, group 1 being the genes least tolerant of losing a copy. Missense variants: 789 observed, 856.99 expected, observed/expected ratio (o/e) 0.92, 90% interval 0.87 to 0.98. Synonymous variants: 295 observed, 293.59 expected, observed/expected ratio (o/e) 1, 90% interval 0.91 to 1.11.
Homologues: Orthologues: macaque FIGNL1 (97% identical), rabbit FIGNL1 (85% identical), dog FIGNL1 (84% identical), pig FIGNL1 (80% identical), guinea pig FIGNL1 (79% identical), rat Fignl1 (78% identical), mouse Fignl1 (77% identical), tropical clawed frog fignl1 (61% identical), zebrafish fignl1 (56% identical), Caenorhabditis elegans figl-1 (36% identical), Drosophila melanogaster Fign (29% identical), Drosophila melanogaster Kat60 (23% identical), and 2 more. Paralogues in human: FIGN (36% identical), SPAST (30% identical), FIGNL2 (26% identical), KATNA1 (24% identical), KATNAL1 (24% identical), VPS4B (23% identical), VPS4A (22% identical), KATNAL2 (21% identical), ATAD1 (16% identical).
Diseases named in the same sentence as FIGNL1 in open-access papers:
FIGNL1 is named in the same sentence as 13 diseases in open-access papers, as found by Europe PMC text mining. Sharing a sentence is not in itself a finding about the gene and the disease. The quoted sentences say what the papers report.
liver cancer (2 papers, 2024). An epithelial or non-epithelial malignant neoplasm that arises from the liver. "Future research will focus on exploring the specific mechanisms by which FIGNL1 contributes to liver cancer, offering new avenues for treatment." (PMID 39428564, 2024). "To further investigate the regulatory effect of FIGNL1 on the growth of human liver cancer cells, we used flow cytometry to further explore the effects of FIGNL1 on cell proliferation and apoptosis." (PMID 37929733, 2024). "In order to verify whether the knockdown of FIGNL1 attenuates the proliferation capacity of human liver cancer cell lines by inducing apoptosis, we first detected the ROS activity of FIGNL1 knockdown cells by flow cytometry." (PMID 37929733, 2024). "As far as we know, there is no relevant research on the molecular mechanism of FIGNL1 in the formation of liver cancer." (PMID 37929733, 2024). "To investigate whether HMMR mediates the influence of FIGNL1 on ECM-receptor interaction pathway remodeling, we used HepG2 human liver cancer cell line to knock down HMMR on the basis of FIGNL1 overexpression." (PMID 37929733, 2024).
hepatocellular carcinoma (1 paper, 2024). A malignant tumor that arises from hepatocytes. "The result indicates that the positive area of FIGNL1 is larger in hepatocellular carcinoma tissue." (PMID 37929733, 2024). "In order to further verify the high expression of FIGNL1 in HCC tissues, we examined the mRNA expression level of FIGNL1 using a hepatocellular carcinoma cDNA chip containing 64 cases of HCC tissues and 26 cases paracancer non-tumor tissues." (PMID 37929733, 2024).
Hypertension (1 paper, 2021). The presence of chronic increased pressure in the systemic arterial system. "The functions of HPS3, FASTKD3 and FIGNL1 have no direct or indirect association with the pathogenesis of hypertension, and the existing studies have not proved their association with hypertension." (PMID 34297769, 2021).
lentivirus infection (1 paper, 2024). Virus diseases caused by the Lentivirus genus. "The regulatory effect of FIGNL1 on HCC was studied by lentivirus infection." (PMID 37929733, 2024). "Meanwhile, stable FIGNL1 overexpression SNU-387 and HepG2 cell lines were constructed by lentivirus infection." (PMID 37929733, 2024).
lung adenocarcinoma (1 paper, 2024). A carcinoma that arises from the lung and is characterized by the presence of malignant glandular epithelial cells. "Importantly, relevant studies have confirmed that FIGNL1 is associated with the development and prognosis of lung adenocarcinoma." (PMID 37929733, 2024). "Recently, relevant studies have reported the role of FIGNL1 in the tumorigenesis of lung adenocarcinoma (LUAD) and other tumors, but its function in HCC malignancy has yet to be said." (PMID 37929733, 2024). "Fidgetin-like 1 (FIGNL1) has been reported to play a vital role in lung adenocarcinoma." (PMID 37929733, 2024).
male infertility (1 paper, 2025). The inability of the male to effect fertilization of an ovum after a specified period of unprotected intercourse. "FIGNL1 is a gene involved in homologous recombination repair, which in mice causes male infertility due to meiotic defects." (PMID 39901712, 2025).
non-small cell lung carcinoma (1 paper, 2022). A group of at least three distinct histological types of lung cancer, including non-small cell squamous cell carcinoma, adenocarcinoma, and large cell carcinoma. "FIGNL1 plays an important role in regulating animal developmental morphogenesis and participates in hydrolase, ATPase, microtubule-severing activities, regulation of double-strand break repair by homologous recombination, and promoting non-small cell lung cancer cell proliferation." (PMID 36362054, 2022).
Premature ovarian insufficiency (1 paper, 2025). Amenorrhea due to loss of ovarian function before the age of 40. "In humans, variations in the FIGNL1 gene have been associated with premature ovarian insufficiency, a disorder characterized by the cessation of menstrual cycles before the age of 40 due to the depletion or dysfunction of ovarian follicles." (PMID 39901712, 2025).
cancer (4 papers, 2021 to 2024). A tumor composed of atypical neoplastic, often pleomorphic cells that invade other tissues. "TCGA data revealed that FIGNL1 is upregulated in various types of human cancer, and compared with normal liver tissue adjacent to cancer, FIGNL1 exhibits a significantly high expression state in HCC tissue." (PMID 37929733, 2024). "Whether FIGNL1 is also expressed in these cancers is unknown." (PMID 37556550, 2023).
tumor (2 papers, 2024). "FIGNL1 has also been shown to promote the growth of tumour tissues and HCC cell lines by re‐establishing HMMR‐mediated ECM‐receptor interaction." (PMID 39428564, 2024). "Here, for the first time, we found that FIGNL1 is highly expressed in human HCC and has a significant or partial correlation with the malignant prognosis and tumor stage of patients, indicating that FIGNL1 has the ability to become a strong predictor of the progression and prognosis in HCC patients." (PMID 37929733, 2024). "Therefore, further study of FIGNL1 may also help to further integrate the extracellular matrix with tumor immunotherapy." (PMID 37929733, 2024).
FIGNL1 also shares sentences with these, for which no sentence is quoted: breast carcinoma (2 papers); glioblastoma (1); Infertility (1).